GALR1 (galanin receptor 1)
Diseases named in the same sentence as GALR1 in open-access papers (continued):
Sharing a sentence is not in itself a finding about the gene and the disease.
tumor (continued). "The fact that GALR1 can down-regulate these cell cycle control genes suggests that it may also exert a tumor suppressor role in HNSCC." (PMID 26251921, 2015). "Our previous studies suggested that GALR1 is a tumor suppressor gene." (PMID 26251921, 2015). "Thus, GAL is antiproliferative by GALR1 and stimulates aggressive tumor growth by GAL2." (PMID 29854027, 2018). "We hypothesized that GALR1 would have a tumor suppressor role in HNSCC." (PMID 26251921, 2015). "The difference in median beta value between tumor and normal samples for colon was 0.13 for ZNF154, while TLX1 and GALR1 showed a difference of 0.70 and 0.60, respectively." (PMID 37835520, 2023). "The average beta value across all tumor-derived cell lines was very high: 0.87 for TLX1, 0.90 for GALR1, and 0.94 for ZNF154." (PMID 37835520, 2023). "Here, we assessed methylation data for TLX1, GALR1, and ZNF154 in cell lines derived from non-tumor (n = 30) or tumor (n = 23) cell karyotypes, and in addition nine cell lines with no designation." (PMID 37835520, 2023). "Our preliminary analyses indicated that methylation-induced galanin receptor type 1 (GALR1) gene silencing is a critical event in HNSCC progression and that restoring expression inhibits tumor cell growth." (PMID 30901947, 2019). "The methylation statuses of the promoters of 11 tumor-related genes (p16, RASSF1A, E-cadherin, H-cadherin, MGMT, DAPK, DCC, COL1A2, TAC1, SST, and GALR1) were analyzed in 133 HNSCC cases using quantitative methylation-specific PCR." (PMID 27027429, 2016). "Consistent with the in vitro findings, the tumor formation and growth rates of both Galanin (GAL) and GALR1 expressing HNSCC cells are significantly reduced in vitro." (PMID 26251921, 2015). "We mined tumor methylation array data from the Cancer Genome Atlas (TCGA) covering 14 cancer types and identified two novel, broadly-occurring methylation markers at TLX1 and GALR1." (PMID 37835520, 2023). "GALR1 showed high methylation in 18/23 tumor-derived cell lines and one non-tumor-derived cell line, GM12878 (B-lymphocytes derived from peripheral blood)." (PMID 37835520, 2023). "However, elevated GALR1 expression in submucosal plexuses in vicinity of CRC correlated with poor prognosis, higher tumour grading and shorter overall survival." (PMID 36551197, 2022). "The average immunoreactivity of GALR1 and GALR3 in muscularis externa plexuses close to the CRC tissue was slightly reduced as compared to the plexuses distant from the tumour, while GALR2 immunoreactivity reminded unchanged (p = 0.0351, p = 0.0204 and p = 0.1109, respectively)." (PMID 36551197, 2022). "The immunohistochemical and immunofluorescent methods showed only slightly decreased immunoexpression of GALR1 and GALR3 in myenteric plexuses close to cancer but did not reveal any correlation in the immunoexpression of all three GAL receptors in myenteric plexuses and tumour progression." (PMID 36551197, 2022).
cancer (18 papers, 2013 to 2026). A tumor composed of atypical neoplastic, often pleomorphic cells that invade other tissues. "To summarize each marker, we found the average of the sensitivity values in tissue samples across all 14 cancer types was 78% for GALR1, 81% for TLX1, and 84% for ZNF154." (PMID 37835520, 2023). "Compared to ZNF154 alone, the addition of TLX1 and GALR1 into a three-marker assay improved the AUC value by more than 0.07 in 4 cancer types." (PMID 37835520, 2023). "In this study we mined TCGA methylation data from 14 cancer types and identified two additional methylation markers for use in combinatorial testing: GALR1 and TLX1." (PMID 37835520, 2023). "Taken together, this shows galR1 may be preferentially upregulated in some cancer types to benefit from its antiapoptotic effects on caspase activation, and addition of galR1 antagonists may prove beneficial as adjunctive therapy." (PMID 41546485, 2026). "YAP1‐mediated proliferation may support evidence of galR1's role in cancer development and proliferation." (PMID 41546485, 2026). "This is consistent with earlier studies that silencing GalR1 could induce apoptosis in cancer cells." (PMID 28203483, 2017). "Although Galanin and GALR1 clearly modulate cell growth and proliferation, we did not observe any effect of either protein on other cancer-associated phenotypes such as apoptosis, invasion potential, and mesenchymal–epithelial transition (MET)." (PMID 26251921, 2015). "Therefore, GALR1 DNA methylation is one common molecular alteration in human cancers." (PMID 30901947, 2019). "We identify two novel, multi-cancer markers in the intronic or promoter regions of TLX1 and GALR1, respectively, and report the benefit of combining them with ZNF154 as a multi-cancer assay." (PMID 37835520, 2023). "Four of the GPCRs, (i) galanin receptor type 1 (GALR1) (ii) GALR2, (iii) tachykinin receptor type 1 (TACR1), and (iv) somatostatin receptor type 1 (SST1) are the most studied and promising therapeutic target in a wide variety of cancer." (PMID 34490084, 2021). "Our study also suggests that GALR1 gene methylation is involved in the prognosis of BLCA, but its role in this cancer is still unknown." (PMID 33150179, 2020). "A critical question is whether galanin and GALR1 can activate MAPK activation in cancer cells, because MAPK is a significant target in cancer therapy." (PMID 26251921, 2015). "In contrast, the correlation between high expression of GALR1 in the submucosal plexuses and overall survival of CRC patients suggest that GAL and GALRs can act as a components of local neuro-paracrine pro-proliferative pathways accelerating the invasion and metastasis of cancer cell." (PMID 36551197, 2022). "We found that GALR1, GALR2 and GALR3 relative immunoreactivity (comparing myenteric plexuses close to CRC cells vs. plexuses distant from cancer invasion) did not correlate with the overall survival of CRC patients." (PMID 36551197, 2022). "We found that GALR1, but not GALR2 and GALR3, relative immunoreactivity (comparing submucosal plexuses close to CRC cells vs. plexuses distant from cancer invasion) correlate with the overall survival of CRC patients (p = 0.0115 and HR = 4.97) and clinical-pathological data of CRC patients." (PMID 36551197, 2022).
heart diseases (1 paper, 2025). "The data on the role of GalR1 and GalR3 in heart diseases are controversial or missing." (PMID 39968178, 2025).
GALR1 also shares sentences with these, for which no sentence is quoted: neuroblastoma (4 papers); pituitary adenoma (3); Crohn disease (2); Xanthelasma (2); Alzheimer disease (1); anaplastic astrocytoma (1); astrocytic tumor (1); cavernous hemangioma (1); Cholestatic liver disease (1); chronic fatigue syndrome (1); diffuse astrocytoma (1); dysentery (1); endometriosis (1); ganglioglioma (1); Glucose intolerance (1); hearing loss (1); infectious disease (1); insulinoma (1); liver fibrosis (1); metabolic disease (1); microtia (1); oligodendroglioma (1); opiate dependence (1); oral cavity cancer (1); ovarian carcinoma (1); pilocytic astrocytoma (1); polycystic ovary syndrome (1); prostate adenocarcinoma (1); psychiatric disorder (1); Rotavirus infection (1).
A further 6 diseases each share a sentence with GALR1 in 1 paper.